CD4 (CD4 molecule)
Diseases named in the same sentence as CD4 in open-access papers (continued):
Sharing a sentence is not in itself a finding about the gene and the disease.
infection (continued). "Naturally, the proportion of CD4+CCR4+ lymphocytes in placebo-treated cats was slightly higher than in uninfected control cats, since FIV-infected cats will mount some Th2 anti-inflammatory response to infection." (PMID 37112803, 2023). "While HSPC susceptibility to HIV infection hinges largely on the expression of CD4, CXCR4, and CCR5, CD4-independent infection mechanisms have been described and should not be discounted for infection of HSPCs." (PMID 37497228, 2023). "While IL-6 induced higher infection rates than resting CD4 + T cells alone, the addition of other cytokines did not induce additional infection." (PMID 37202790, 2023). "Further, restimulation of PBMCs 7 and 14 days after infection with SARS-CoV-2 spike protein did not result in an increase in CD4+ and CD8+ subsets within the PBMCs." (PMID 37243138, 2023). "As expected, large numbers of CD4 and CD8 T cells produced Ifnγ at day 10 post infection." (PMID 37842651, 2023). "Similarly, CD4+TIM-3+ and CD8+TIM-3+ cells achieved analogous percentages at 30 (4-5%) and 60 (10-11%) days of infection." (PMID 37691941, 2023). "Placental CD4+Treg cells were increased by 61%–97%; however, a functional activation of Treg cells in response to vaccination and/or infection was not noted." (PMID 38104118, 2023). "This suggests that the greater protection of Nur77-GFPHI CD4 T cells is not due to a difference in surviving cell numbers accessing the infection site, but instead to functional characteristics enriched in the activated Nur77-GFPHI CD4 T cell population." (PMID 38110410, 2023). "The expression of adaptive immune response genes, mIgM, CD4 and CD8a was significantly upregulated in heart tissues of PRV-1 infected fish, indicating both B/T cell mediated immune responses and influx of B and T cells to the site of infection/inflammation." (PMID 37644605, 2023). "The immune response in vaccinated or immune individuals is known to be faster and more potent upon infection, likely enabling more rapid containment of microbial pathogens which could involve the ZEB2+ cytolytic memory CD4+ T cells." (PMID 38001069, 2023). "Depletion of CD4+ Th cells from PBMCs isolated on day 7 after infection substantially reduced IL-17A production in response to stimulation with CS6 and CS5, supporting that the observed IL-17A responses to CFs were derived from CD4+ Th cells." (PMID 37809062, 2023). "Interestingly, apart from the decrease in LY6C- monocytes, Ts65Dn mice presented with a significantly higher CD4+/CD8+ T cell ratio at baseline level, which further increased as infection prolonged." (PMID 37112973, 2023). "Surprisingly, while preexisting CD4+ T cells enhanced the influx of total germinal center (GC) B cells in the mediastinal lymph node after infection, this was not reflected by an increase in the frequency of antigen-specific cells within the GC." (PMID 37711622, 2023). "However, IL-27 is required to maintain virus-specific CD4 T-cell numbers after chronic viral infection but also influences IFN-I, DC, and NK cell responses early after infection." (PMID 37583704, 2023). "Effective clearance of T. pallidum at sites of infection occurs through the induction of a delayed-type hypersensitivity (DTH) response, which is mediated by the infiltration of CD4+ T cells and the activation of macrophages to phagocytose and kill T. pallidum." (PMID 37795301, 2023). "The early expression of CD4 + T and CD8 + T cells during infection may suggest their regulatory function in the sustenance and proliferation of protoscoleces." (PMID 38072840, 2023). "On the other hand, SARS-CoV-2-specific CD4+ T cells at the pre-vaccination time point from donors with a history of natural infection were enriched in a TCM phenotype, further supporting the notion that they are long-lived memory cells." (PMID 37575243, 2023).
infection (continued). "Although total T cells and CD8 + T cells were not significantly different between groups, CD4 + T cells were significantly diminished in our coinfected mice compared to CS-exposed mice without infection." (PMID 37065141, 2023). "CD4+ T cells and interferon-gamma (INF-γ) were found to be the dominant immune agents against murine C. parvum infection as the IFN-γ produced by these cells is required for infection clearance." (PMID 37858196, 2023). "Notably, infection of neonatal mice with RSV enhanced the airway hyperreactivity response to subsequent allergen challenge, with higher eosinophil, macrophage and CD4+ T cell accumulation and elevated IL-4, IL-5 and IL-13 cytokines." (PMID 37795093, 2023). "These endocytic fusion events are likely culminating inproductive infection since endocytic inhibitors, such as EIPA, Pitstop2,and Dynasore, as well as a dominant-negative dynamin-2 mutant, inhibitedHIV-1 infection in HeLa-derived and primary CD4+ T-cells." (PMID 37589658, 2023). "During the infection, the regular pathway to produce IgG antibody is highly related to the proliferation of SARS-CoV-2-specific CD8+ or CD4+ T cells, which is reflected by the elevated secretion of several typical cytokines, including interleukin-5 (IL-5) and interferon-γ (IFN-γ)." (PMID 37391398, 2023). "Recombinant IL-6 cytokine did not increase infection in activated CD4 + T cells by itself, nor did the anti-IL-6 antibody interfere with IEC stimulation." (PMID 37202790, 2023). "At 1 month post-infection, 97.5% of participants had a positive response for non-S-specific CD4 + T cells, and 88.7% of participants maintained a positive response after 20 months." (PMID 37974069, 2023). "For the homologous boosters, higher HIV DNA levels pre-infection were strongly negatively correlated with lower baseline CD4 counts (r = −0.6469, p = 0.0005) rather than HIV CA-RNA (r = −0.3154, p = 0.1246)." (PMID 38140668, 2023). "On the other hand, CD4+ T cell counts was significantly lower in PLWH with Bh infection compared to those without Bh infection (Z = 8.226, P < 0.001)." (PMID 37697423, 2023). "The baseline CD4+ T cell count (p < 0.0001) and baseline CD4+ T/CD8+ T ratio (p = 0.0006) of all HIV-1 R5-tropic infections were, respectively, higher than those of X4-tropic infections." (PMID 37152735, 2023). "These mice exhibited progressive weight loss and failed to control bacterial growth in the absence of CD4+ T cells, succumbing to infection shortly after the week 8 time point." (PMID 37733817, 2023). "Additionally, at 12 days post-infection, the spleen of CKO mice showed a decrease in the number of CD4+ T cells producing IL-10 compared to WT mice." (PMID 37908369, 2023). "No consistent changes in eosinophils, neutrophils, B cells, CD4+ or CD8+ αβ T cells or γδ T cells were observed post-infection." (PMID 37012228, 2023). "However, further insights into the regulation of CD4+ and CD8+ T cell responses are needed to allow a better understanding of infection control and host damage limitation during persistent infection." (PMID 37065193, 2023). "In contrast, in the majority of participants from the breakthrough infection group, MNE- and/or S-specific CD4+ and CD8+ T cells could readily be identified." (PMID 37215123, 2023). "Lastly, examination of cytokine production at later times after infection indicated that CD4+ T cells did not maintain their ability to produce IL-10 at a higher rate in the absence of Bhlhe40." (PMID 37843306, 2023). "The proportion of PbT‐II cells in PB and the number of PbT‐II cells in spleen did not decrease, although the total number of CD4+ T cells decreased 14 days after infection (Fig EV5B and C)." (PMID 37855243, 2023). "However, BA.5 and its parental strain, B.1.1.529, infection leads to the similar frequency of IFN-γ, IL-17A, IL-10-producing CD4+ T cells as well as IFN-γ, IL-10-producing CD8+ T cells in BALF." (PMID 37704701, 2023).
infection (continued). "IFN-γ is a potent inflammatory and regulatory cytokine that is also elevated in the lungs following PR8 infection, and is required for the activation of CD8+ cytotoxic and CD4+ helper T cells and also helps control neutrophilic infiltration in the lung, thereby limiting tissue damage." (PMID 36845136, 2023). "However, mature LCs have decreased langerin expression, suggesting that other receptors (i.e. CD4 and CCR5) play a role in virus binding and subsequent infection." (PMID 36841916, 2023). "However, the Ts65Dn mice tend to have an overall higher CD4+/CD8+ T-cell ratio compared to the WT mice, and this difference was significant after seven days of rhRSV-Luc infection." (PMID 37112973, 2023). "Upon exposure to Cn antigens, microglia can recruit peripheral macrophages and CD4+ or CD8+ cells to further respond to local infections, without which the host quickly succumbs to disease." (PMID 36902168, 2023). "Likewise, in secondary infections in healed genetically resistant mice, a DTH response was shown to be mediated by both CD4+ and CD8+ T cells upon challenge with live promastigotes." (PMID 37919280, 2023). "Effector memory T cells expressing more CCR5 show higher percentages of infection by HIV-1 type C, but all CD4 T cell subsets could be infected." (PMID 36742330, 2023). "As in pre-patent infection, a significant proportional reduction in BAL eosinophils was observed in Cre+ mice, along with a significant proportional and absolute reduction in BAL CD4+ T cells by this d49 timepoint." (PMID 37012228, 2023). "Gating overlay of lymphoid cell subsets in t-sne dimension 1 and 2 indicated lower density of CD4 and CD45 clusters in the spleen at 30 days post-infection, while the density of clusters remained identical for WT and Duox1 KO at 1 day post-infection." (PMID 36936954, 2023). "This forced us to abandon using the CD4+ T cell decline as the measure of virulence and to develop an alternative quantitative measure of HIV-1 virulence that incorporates the CD4+ T cell level immediately after primary infection." (PMID 37161335, 2023). "Given that seropositive subjects recruited had not been previously vaccinated, this data highlights that infection/exposure alone has the capacity to induce spike-specific polyfunctional CD4 + T-cells beyond Ab responses." (PMID 37709772, 2023). "Activated CD4+ and CD8+ T cells are recruited into the cornea by MIP-1α by day 5 post-infection." (PMID 37630634, 2023). "AVS had no consistent effect on SARS-CoV-2-specific memory CD4+ or CD8+ T cell responses 6 months post-infection." (PMID 37134108, 2023). "Moreover, the expression of immune-related genes (SAA, iNOS, IL-1 β, IL-6, IL-10, TNF α, C3, MHC I, MHC II, CD4, CD8, TCR α, IgM, IgD and IgZ) increased in all groups post infection, which was more significant in the vaccinated groups." (PMID 36969197, 2023). "The overall (although inconsistent) increase in speed and turning angle of both CD4 and CD8 T cells with time since infection may be related to the need for T cells increased efficiency of search for pathogen at later times after infection." (PMID 37811200, 2023). "There was an increase in Rora+CD4 T cells and CD45+CD3+CD4+GATA3+ cells in the lungs of mice postinfection, with the highest frequency in cells during a secondary infection." (PMID 37387671, 2023). "Unfortunately, we were not able to establish a link between CD4+-T-cell numbers and infections in general." (PMID 37152008, 2023). "CD4+ T cells from these mice exhibited higher IFN‐γ production in response to Plasmodium antigen and higher anti‐Plasmodium antibodies in the serum 63 days after infection." (PMID 37855243, 2023). "Cationic peptide dendrimers which bind to cell surface glycosphingolipids block the infection of not only lymphocytes and macrophages but also CD4-negative cells by several HIV-1 and HIV-2 strains." (PMID 36851498, 2023).
infection (continued). "Changes in CD4+ followed a similar pattern as previously seen, but we did not observe the rapid initial increase in CD4+ T cells after infection that is typically accompanied by sharp increases in viral and proviral loads." (PMID 37112803, 2023). "At 10 months post-infection, there was a significant decrease of both S-specific CD4 + and CD8 + T cells (Median: S-small pool: 0.11% and 0.05% for CD4 + and CD8 + T cells, respectively; S-large pool: 0.69% and 0.42% for CD4 + and CD8 + T cells, respectively)." (PMID 37974069, 2023). "Whilst we did demonstrate a significantly higher proportion of infection within CD4+ and CD4+/CD8+ MAIT cells, the biological impact of this is not clear given they represent a small subset of the overall MAIT cell compartment." (PMID 37006246, 2023). "Indeed, primary infection results in the oligoclonal expansion of a set of Th1-like, EBV-specific CD4+ T cells." (PMID 38179040, 2023). "In conclusion, we suggest that CD4+ TEMRA cells may be impaired with respect to their metabolic response to stimulation, possibly contributing to impaired responses to infection and vaccination." (PMID 37106796, 2023). "In individuals without previous natural infection, the CD4+ T cell response to the S proteins exhibited an increase in magnitude upon vaccination." (PMID 37575243, 2023). "Functional analysis validated that Ly6C+Ly6G+CD4+ T cells cooperate with Mφ against APP-induced infection in mice (data not shown)." (PMID 37705063, 2023). "In contrast, numbers of CD4+ T-lymphocytes decreased in 10403s-infected mice to the degree that they were not different 4 mo after infection compared to uninfected or Δhly Lm infected mice." (PMID 37143648, 2023). "Activated CD4+ T cells were infected with HIVNL4-3 and treated with fentanyl after infection." (PMID 37113007, 2023). "In the present study, we demonstrated that after co-culturing iDCs or mDCs with captured HIV-1 and GPI-scFv-transduced CD4+ cell lines as well as human primary CD4+ T cells, the anti-HIV-1 GPI-scFv X5 inhibitor almost completely blocks trans-infection of the target cells." (PMID 37781368, 2023). "Even in female mice depleted of CD4+ and CD8+ T-cells, disease was milder than isotype-treated male mice suggesting that even in mice lacking cellular immunity, female mice retain better control of the infection than male mice." (PMID 37866114, 2023). "Differences in number of CD3 + T cells, CD3 + CD4 + T cells, and CD3 + CD8 + T cells were significant between both groups (P < 0.05), which were significantly higher in the normal population than in the patients with asymptomatic OMICRON infection." (PMID 37408049, 2023). "Activation-induced marker assay revealed an increase in CD4+ (but not CD8+) T cells post infection, comparable to previously infected healthy controls." (PMID 38023562, 2023). "In contrast to these findings, a different group found the same epitope activated CD4+ T cells in more donors with breakthrough infections after vaccination compared to vaccinated donors with no breakthrough infection." (PMID 36851285, 2023). "Although lower CD4+ counts did not lead to a significantly higher number of distinct anal hrHPV types, anal hrHPV infections were significantly more prevalent in HIV-infected women than in HIV-uninfected women (Chi-square test p < 0.001)." (PMID 37376627, 2023). "Lymphopoiesis could also be differently altered in our model of experimental CD4+ T-cell depletion, compared to HIV/SIV progressive infections, and it has been previously shown that exhaustion of lymphopoiesis can drive disease progression." (PMID 36813761, 2023). "Considering the correlation between the CD4 count and infection, a moderate and negative correlation was detected with HIV RNA viral load, and a similar negative correlation was detected with CMV infection." (PMID 37887742, 2023).
infection (continued). "To that end, we incubated CD4+ T cells with Sotrastaurin (AEB071; 40 μM), a cell-permeant inhibitor of PKC63, during their 48-h activation with PHA and IL-2 and the subsequent 6-h infection with HIV-89.6-EGFP." (PMID 37563144, 2023). "We used Poisson and quasi-Poisson segmented regression models to estimate the immediate and long-term impact of treat-all on three key indicators: monthly proportion of 30-day ART initiation, mean CD4 counts (cells/μl) at ART initiation, and mean estimated time from infection to diagnosis (year)." (PMID 37580822, 2023). "While B cells enhance expression of FoxP3 and decrease expression of CD44 and T-bet by CD4+ T cells in the first two weeks after infection, we found expression of CD44, T-bet, and FoxP3 was similar in CD4+ T cells from WT and MD4 mice at one- and two-weeks post-infection." (PMID 37721965, 2023). "Moreover, individuals who recovered from SARS-CoV-1 infection had SARS-CoV-2 cross-reactive CD4+ and CD8+ T cells 17 years after infection." (PMID 37114047, 2023). "CD4+ T cell depletion at the time of infection, but not at later stages, led to viral persistence, indicating that CD4+ T cells function to prime HBV-specific immune responses." (PMID 37948314, 2023). "Consistent with their findings and a role for Hla in limiting the expansion of immune cells, we found that the total number of CD3+, CD4+, CD8+, γδ T cells, and CD11c+ DCs 1 week after infection were higher in draining LNs in the mice infected with Δhla, compared with WT." (PMID 36693884, 2023). "In summary, post–BT infection in vaccinated patients with HM, there was a significant CD4+ T-cell and Tfh rise but not CD8+ T-cell rise, with no impact on prior receipt of B-cell–depleting therapy in the last 12 months." (PMID 38023562, 2023). "While CD8+ T cells recognize and kill the infected cells, CD4+ T cells contribute to activate B cells for antibody secretion and CD8+ T cells to exert the cytotoxic activity, and to produce cytokines that favor immune cell migration at the site of infection." (PMID 37662901, 2023). "Further analysis of CD44+CD4+ T cells in WT animals revealed FoxP3 expression was preferentially enhanced among CXCR5+ populations vs CXCR5- populations (15.40% ±1.93% vs 3.6 ±1.22) at two- and four-weeks post infection." (PMID 37721965, 2023). "When we interpolated our results with clinical data, we remarked that in mothers with ongoing infection, delayed umbilical cord clamping led to a selective enrichment of NK cells, but not of B or CD4+ T cells, in the cord blood." (PMID 37490342, 2023). "Thus, CD4 effector and regulatory subsets are variably affected in STAT1 GOF patients, however it remains unclear if this variability reflects specific STAT1 GOF mutation impacts and/or environmental influences such as infections or immunosuppressive treatments." (PMID 37275873, 2023). "At week 2 post-infection and treatment, the lungs from JHU083-treated mice showed a statistically significant 25% higher frequency of CD4+ T-cells (mean = 36.9% of live CD45+) compared to both untreated (mean = 29.5% of live CD45+) and RIF-treated mice (mean = 24.5% of live CD45+)." (PMID 37973991, 2023). "Since no viral production was observed during the cis-infection of mDCs with these strains, our results suggest that the production of infectious viral particles is induced by the co-culture of mDCs with CD4+ T lymphocytes." (PMID 37243118, 2023). "We further explored the function of CD4+ and γδ T cell responses in AE-IPF, and our data showed that the levels of IL-17 secreted from CD4+T and γδ T cells were significantly increased after NT127 infection following BLM instillation." (PMID 35836804, 2022). "Both CD4 and CD8 TRM reside in mucosal could be produced by natural infection; however, natural infection could be lethal." (PMID 36471700, 2022).